PIK3CA (phosphatidylinositol-4,5-bisphosphate 3-kinase catalytic subunit alpha)
Diseases named in the same sentence as PIK3CA in open-access papers (continued):
Sharing a sentence is not in itself a finding about the gene and the disease.
adenoma (39 papers, 2011 to 2026). A neoplasm arising from the epithelium. "Activating mutations in PIK3CA are seldom detected in adenomas and are instead restricted to cancers." (PMID 34245130, 2022). "Two high-risk cases were distinguished by the presence of BRAF p.V600E and PIK3CA p.E545K mutations, whereas one adenoma of the low-risk cases showed NRAS p.G12D." (PMID 34372923, 2021). "In previous studies, somatic mutations in KRAS, BRAF, and PIK3CA have been found in CRC or adenomas from other germline gene mutation carriers." (PMID 34549727, 2021). "We also found PIK3CA mutations in three samples, two of which were adenoma-private (AC29, p.E545K; and AC40, p.E542K)." (PMID 32895052, 2020). "PIK3CA mutations are rare in in colon adenoma, but often occur in advanced adenomas greater than 5 cm in diameter." (PMID 28179590, 2017). "There is evidence to suggest PIK3CA mutations occur early in tumorigenesis, possibly at the transition between adenoma and carcinoma." (PMID 28206962, 2017). "We observed a very low frequency of PIK3CA mutations (3%) in our tumor samples (adenomas and T1 cancers), consistent with previous studies." (PMID 25093594, 2014). "The type and distribution of mutations in PTEN exons 7 and 8 and PIK3CA exons 8, 9 and 20 in 186 adenocarcinoma and 16 adenoma samples available from EPIC Norfolk." (PMID 21473780, 2011). "Also, PIK3CA mutations are found in cancer-associated adenomas (20.0–30.0%), or lower frequency in advanced adenomas (3.2%), similar to the frequency observed in our study." (PMID 35761395, 2022). "However, PIK3CA mutations are less common in colorectal adenomas, around 3%, indicating that mutations in PIK3CA would generally arise later during the adenoma-carcinoma transition." (PMID 35173208, 2022). "In our study, the HGCA10 with PIK3CA mutation was found in a large adenoma (3.7 cm in diameter) with a synchronous carcinoma component, suggesting that the HGCA case may be a full-grown late-stage one." (PMID 28179590, 2017). "Interestingly, mouse models with simultaneous induction of pathogenic mutations in Apc, Kras and Pik3ca still progress through a histological adenoma-to-carcinoma sequence, further demonstrating that mutational profile of the tumour is not predictive of the stage of the disease." (PMID 27609830, 2017). "This study is aimed at evaluating the frequency of KRAS-G12C and PIK3CA-Q546K in adenomas and CRC from MAP patients and to demonstrate their relevance to reclassify MUTYH VUS." (PMID 42164324, 2026). "It is well known that widely invasive malignancies have a distinct profile, including activation of the PIK3CA-Akt-mTOR and Wnt/b-catenin pathways and that adenomas cluster with minimally invasive carcinomas." (PMID 38882980, 2024). "Here we validate BaseScope ISMD technology and use it to map the topography of subclones bearing driver mutations in one of the KRAS, PIK3CA or BRAF proto-oncogenes in CRCs and adenomas." (PMID 29222441, 2017).
adenoma (continued). "In the step-wise genetic alteration model associated with colorectal tumorigenesis, PIK3CA mutations occur after KRAS or BRAF mutations and, in cooperation with other mutations, drive clonal evolution from large adenoma to invasive adenocarcinoma." (PMID 26498038, 2015). "They investigated the genomic profiles of 5 paired adenoma and invasive carcinoma tissues and found that PIK3CA mutations were only present in two of five carcinoma tissues and not in the adenoma." (PMID 29069792, 2017). "PIK3CA mutations may, however, suggest benefit from aspirin for secondary prevention, since large studies have demonstrated that aspirin reduces adenoma and CRC formation in individuals with PIK3CA-mutated primary CRC." (PMID 26337942, 2015). "This single PIK3CA mutated adenoma presented in an individual as an isolated neoplasm, without concurrent adenocarcinoma." (PMID 21473780, 2011). "KRAS-G12C was also present in 47% of 17 MAP adenomas, whereas none of them harbored PIK3CA-Q546K." (PMID 42164324, 2026).
lung squamous cell carcinoma (38 papers, 2012 to 2026). "Therapeutic efficacy was further evaluated in a patient-derived xenograft (PDX) model of lung squamous cell carcinoma harboring the PIK3CA E545K mutation." (PMID 41934916, 2026). "In squamous cell lung cancer cells, it has been observed that newly generated PIK3CA-mutated SQCLC cells showed increased growth rate and enhanced migration and invasiveness." (PMID 37553597, 2023). "The frequency of PIK3CA mutation, as determined by direct sequencing was 3.9% in lung squamous cell carcinoma and 2.7% in adenocarcinoma, which is comparable to the value of 2.9% and 2.5% in a previous report which examined a small number of Japanese patients." (PMID 24533074, 2014). "In this study, PIK3CA mutation was relatively frequent in squamous cell lung cancer, as reported in other studies, while FGFR1 copy number gain seemed less frequent." (PMID 25348872, 2014). "Copy number gains of up to 43% in lung squamous cell cancer were demonstrated suggesting that amplifications of PIK3CA are more frequent than mutations." (PMID 23936763, 2013). "Besides, it has shown anti-cancer efficacy in squamous cell lung cancer cells with PIK3CA mutation in vitro and in vivo." (PMID 37553597, 2023). "This preferential activity in H23/H460 lines correlates with PIK3CA alterations prevalent in 33.1% of lung squamous cell carcinomas which sensitize tumors to PI3K/Akt pathway modulation." (PMID 40649280, 2025). "The squamous cell lung carcinomas showed two cases with ARID1A loss of function variants (E1718* and G1848fs), one FGFR3 S249C variant, one MAP2K1 P124L, and one case with PIK3CA amplification and E545A variant." (PMID 36125633, 2023). "In 134 lung squamous cell carcinoma tissue samples, there were 7 (5.2%) EGFR mutations, 6 (4.5%) KRAS mutations, 12 (9.0%) PIK3CA mutations, 1 (0.7%) BRAF mutations and 1 (0.7%) MET amplifications." (PMID 31749831, 2019). "In 96 lung squamous cell carcinoma blood samples, there were 8 (8.3%) EGFR mutations, 7 (7.3%) KRAS mutations, 6 (6.3%) PIK3CA mutations and 1 (1.0%) BRAF mutations." (PMID 31749831, 2019). "Amplification of PIK3CA in the 3q locus (3q26) is also a mechanism of oncogene activation in squamous cell lung cancer." (PMID 23936763, 2013). "PIK3CA mutation and FGFR1 amplification both represent potential targets for personalized squamous cell lung cancer therapy, and it may therefore be important to analyze both these gene alterations in clinical practice." (PMID 25348872, 2014). "Furthermore, the PIK3CA gene has been recognized as a candidate driver gene of lung squamous cell carcinoma and may contribute to the tumor cell growth and development of NSCLC." (PMID 32908885, 2020). "There were repeat copies of PIK3CA and ECT2 in approximately 45% of patients in a TCGA lung squamous cell carcinoma cohort." (PMID 27029057, 2016).
small cell lung carcinoma (36 papers, 2012 to 2026). Small cell lung cancer (SCLC) is a highly aggressive malignant neoplasm, accounting for 10-15% of lung cancer cases, characterized byrapid growth, and early metastasis. "PIK3CA was also found frequently mutated in small-cell lung cancer (SCLC)." (PMID 31426419, 2019). "In addition to EMT, PIK3CA mutations, and conversion to small cell lung cancer histology are other mechanisms that have been implicated in resistance to EGFR inhibition." (PMID 24722523, 2014). "In addition to the drug resistance conferred by the C797S mutation in EGFR, amplification of the MET gene as a bypass pathway, alteration in RAS-RAF-MAPK pathway, ROS1 fusion gene, PIK3CA mutation, and transformation to small cell lung cancer are other mechanisms that impart drug resistance." (PMID 34831415, 2021). "Possible mechanisms lead to primary resistance in first-generation EGFR-TKIs include PIK3CA mutations, MET amplification, BIM polymorphism, changes in the PIK3CA-AKT-mTOR signaling pathway, and the transformation from NSCLC to small cell lung cancer." (PMID 37791062, 2023). "Additional mechanisms include amplification of the MET gene, PIK3CA mutation, BRAF mutation, epithelial-to-mesenchymal transition (EMT), and small cell lung cancer (SCLC) transformation." (PMID 27821131, 2016). "PIK3CA alterations were observed in approximately 20% of EGFR-mutated small-cell lung cancer cases, although no statistically supported association with never-smoker status can be concluded from these data." (PMID 41594221, 2026). "In the case of T790M loss, several genetic alterations have been observed, including those related to transformation to small cell lung cancer, MET amplification, ERBB2 amplification/mutation, PIK3CA mutation, KRAS mutations, and oncogenic gene fusion involving RET, FGFR3, and BRAF." (PMID 34831415, 2021). "Several mechanisms leading to acquired resistance have been demonstrated, including EGFR T790M mutation, MET amplification, PIK3CA mutation, AXL activation, small cell lung cancer (SCLC) transformation, or acquiring an epithelial-to-mesenchymal transition (EMT) phenotype." (PMID 29717264, 2018). "Other aberrations that may give rise to EGFR TKI resistance include PIK3CA mutations, EMT or MET amplification, or conversion to small cell lung cancer histology." (PMID 22363766, 2012). "In addition, other acquired resistance mechanism has been reported; including the development of small cell lung cancer or squamous cell transformation, second point mutations (D761Y or L747S), MET amplification, acquired PIK3CA or BRAF mutation, and epithelial-to-mesenchymal transition." (PMID 26862733, 2016). "When compared to small-cell lung cancer (SCLC), SCNCC samples demonstrated notably higher frequencies of genomic alterations in PIK3CA (24% vs. 5.1%), MYC (12.7% vs. 6.3%), ARID1A (10.1% vs. 4.2%), and MSI-High (3.1% vs. 0.004%)." (PMID 38793044, 2024). "Alternative signaling pathways, such as MET amplification, may also be activated, as are other mechanisms such as HER2 amplification, PIK3CA, KRAS, BRAF, and small cell lung cancer transformation." (PMID 39231972, 2024).
endometrioid carcinoma (32 papers, 2013 to 2026). "The authors also preclinically tested the PI3K inhibitor AZD8835 in two subrenal xenografts, an endometrial clear cell carcinoma harboring a PTEN deletion and an endometrioid carcinoma harboring a PIK3CA mutation." (PMID 39682182, 2024). "PIK3CA mutation in ctDNA was frequently detected in endometrioid carcinoma cases (2/5; 40.0%), followed by OCCC cases (3/13; 23.1%), which is consistent with previous tissue DNA studies." (PMID 33207545, 2020). "PT492, the fourth stage 1A, grade 1 endometrioid adenocarcinoma case, had one driver mutation detected in PIK3CA (G106V; cell pellet DNA)." (PMID 28027320, 2016). "Activating mutations of PIK3CA are found in 20% of endometrioid carcinomas, while mutations in PTEN are present in 14-20%, and loss of heterozygosity of PTEN was present in 42%." (PMID 27231561, 2015). "In endometrioid carcinoma, PIK3CA and SLITRK5 mutations were detected frequently (40%)." (PMID 33207545, 2020). "employed a 4-gene panel (CTNNB1, PTEN, KRAS, and PIK3CA) to analyze paired plasma and tumor tissues from 48 cases of endometrioid carcinoma." (PMID 40860812, 2025). "Clear cell carcinoma is defined by ARID1A, PIK3CA, and TERT promoter mutations, and endometrioid carcinoma is defined by PTEN and PIK3CA mutations." (PMID 39364049, 2024). "OCCC and endometrioid carcinomas also have in common a disrupted PTEN-PI3K pathway with mutations observed in PTEN and PIK3CA, as well as mutations in CTNNB1." (PMID 35223797, 2022). "In endometrioid carcinoma, PTEN mutations are associated with other mutations found in KRAS proto-oncogene, Catenin Beta 1 (CTNNB1), and PIK3CA genes and microsatellite instability, which results in short DNA sequence alterations and its ultimate replication." (PMID 34322276, 2019). "Clear cell carcinoma is characterized by ARID1A, PIK3CA, TERT promoter mutations, and endometrioid carcinoma is characterized by PTEN, PIK3CA, ARID1A, and CTNNB1 mutations." (PMID 31130643, 2019). "The mutations of PIK3CA and CTNNB1 genes, as well as the alteration of the SWI/SNF complex, that was documented in our case by the loss of ARID1A expression, are among the most common and earliest genetic abnormalities detected in endometrioid carcinoma." (PMID 34342838, 2022). "A CTNNB1 mutation was revealed to be critical in the growth of ovarian steroids retaining preneoplastic epithelial cells with PTEN and PIK3CA mutations and myometrial invasion of endometrioid carcinoma in castrated mice harboring PTEN LOF and PIK3CA activating mutations." (PMID 34036097, 2021). "Endometrioid carcinoma patients had a high prevalence of concurrent mutations of ARID1A, PTEN and PIK3CA and could therefore be easily identifiable candidates for a combination of inhibitors of PARP and the MTOR pathway." (PMID 33947352, 2021).
endometrioid carcinoma (continued). "PIK3CA variant was identified with VAF 82.8% in NEC, 75.2% in endometrioid carcinoma, 37.2% in ovarian endometriosis, and 77.2% in uterine EAH, while CTNNB1 variant was identified with VAF 76.9% in NEC, 64.6% in endometrioid carcinoma, 16.3% in ovarian endometriosis, and 68.7% in uterine EAH." (PMID 34342838, 2022). "In ten cases in which no PIK3CA mutation was found in the tumor (eight HGSOC, one endometrioid carcinoma, and one mucinous carcinoma), PIK3CA mutation was detected only in the Pap smear or plasma sample." (PMID 34172890, 2021).